BRD4 (bromodomain containing 4)
Diseases named in the same sentence as BRD4 in open-access papers (continued):
Sharing a sentence is not in itself a finding about the gene and the disease.
cancer (continued). "Post-translational modifications have been identified to be of great importance in cancers and lysine acetylation, which can attract the multifunctional transcription factor BRD4, has been identified as a potential therapeutic target." (PMID 25603177, 2015). "Recently, BRD4 has been demonstrated to play a key role in the pathogenesis of several different types of cancers and is considered to be a compelling therapeutic target." (PMID 25603177, 2015). "This is in contrast to the effects of suppressing BRD4, a more general cofactor that is essential for the maintenance of many cancer types and for the homeostasis of several normal tissues." (PMID 25919951, 2015). "As Brd4 represents a novel and promising drug target for cancer therapy, it is crucial to thoroughly elucidate its role in cell cycle progression and in epigenetic and transcriptional regulation." (PMID 24592384, 2014). "The BET family protein Brd4 is a promising therapeutic target for the treatment of cancer, and early-generation BET inhibitors are being evaluated in phase 1/2 clinical trials." (PMID 25242322, 2014). "The interaction of the first bromodomain (BD1) of Brd4 with acetylated NF-κB/RelA leads to constitutively active NF-κB that enhances cancer cell proliferation." (PMID 24592384, 2014). "Accordingly, small molecule inhibitors targeting Brd4 have been proven to be a promising drug for cancer therapy." (PMID 24592384, 2014). "An essential role of BRD4 in cell proliferation and cancer growth has been reported in several recent studies." (PMID 24497639, 2014). "For example, drugs such as triptolide that targets the general transcription factors TFIIH and JQ1 to inhibit BRD4 are administered to target the high proliferative rate of cancer cells." (PMID 24576043, 2014). "While the amplifications of SETDB1 and BRD4 have been previously identified and their roles in cancer have been well-studied, less is known about the functions of YEATS4 and NSD3 in cancer." (PMID 24874471, 2014). "In particular, we identified the epigenetic regulatory genes NSD3, SETDB1, YEATS4, and BRD4 as putative amplified cancer drivers in several cancer types." (PMID 24874471, 2014). "The BET BRD4 protein plays a major role in cancer development as a reader of acetylated histones, and first clinical studies with inhibitors targeting BET bromodomains have already been initiated." (PMID 24497639, 2014). "Most recently, Vakoc has found three other major protein players (Menin, Ezh1/2 and Eed) that work together with BRD4 to make MLL-AF9 AML incurable by currently deployed anti-cancer drugs." (PMID 23303309, 2013). "Knockdown of Brd4 has been shown to lead to reduced expression of the Myc oncogene, suggesting a likely mechanism by which Brd4 plays a role in cancer." (PMID 24704920, 2012). "We identified BRD2 upregulation as a conserved response to BET inhibition across multiple cancer types and hypothesized that BRD2 compensates for BRD4 loss, sustaining essential transcriptional programs upon treatment." (PMID 42069518, 2026). "We find that the cancer-related truncated variants comprising residues 1-645 and 1-591 of ASXL1 (ASXL11-645 and ASXL11-591) retain BRD4 binding function, with ASXL11-645 showing an enhanced ability to recruit BRD4 to promoters of ASXL1 target genes." (PMID 41702923, 2026). "BRD4 plays a pivotal role during embryogenesis and cancer development, but its function in modulating β‐cell differentiation remains unknown." (PMID 40539402, 2025). "BRD4 inhibitor and degrader are regarded as promising epigenetic cancer therapies." (PMID 39816690, 2025). "Despite the structural similarities between BRD4 and BRDT, it is unclear whether the functions of ectopically expressed BRDT are unique and/or redundant to the functions of the ubiquitously expressed BRD4 in cancer cells." (PMID 40085698, 2025). "BRD4 was eliminated from cancer cells using CRISPR, which slowed the development of tumours." (PMID 41394966, 2025).
cancer (continued). "In addition, this work demonstrates the versatility of HSP70-based PROTACs by effectively degrading additional endogenous bromodomain-containing protein 4 (BRD4) in cancer cells." (PMID 41387312, 2025). "BRD4 is often overexpressed in many cancers thus making BRD4 as an attractive therapeutic target." (PMID 40370549, 2025). "JQ1, an inhibitor of BRD4, effectively disrupts SE activity in various cancers." (PMID 39915455, 2025). "Recently, BRD4 has gained attention as a potential therapeutic target in cancer treatment." (PMID 41249136, 2025). "Similarly to CDK9, CDK7 also has a bidirectional relationship with BRD4 whereby both are substrates for each other, creating a regulatory loop that is important for gene transcription in cancer." (PMID 40163908, 2025). "A comprehensive understanding of the transcriptional alterations induced by BRD4 inhibition could elucidate the anti-tumor mechanisms of BET inhibitors and improve the efficacy of BRD4-targeted therapies in cancer treatment." (PMID 41249136, 2025). "In addition, BRD4 exerts protective effects in various types of cancer by binding key enhancers to drive the expression of apoptosis resistance genes." (PMID 40032852, 2025). "Additionally, our cell line models express low endogenous levels of the BRD4(b) short isoform, limiting our interpretation of how amplification of this isoform impacts cancer cell fitness." (PMID 40112818, 2025). "BRD4 inhibition has been shown to have a modest direct antitumor effect through induction of cell cycle arrest, apoptosis, and modulation of oncogene expression in cancer cells." (PMID 40762981, 2025). "Inhibitors targeting BRD4 show great potential for cancer therapy." (PMID 41184230, 2025). "The compound demonstrated robust protein degradation up to 98% at 100 nM concentrations and improved anticancer efficacy compared to previously reported BRD4 PROTACs across various cancer cell types, including colorectal cancer, melanoma, and lung cancer cells." (PMID 40507351, 2025). "Thus, PDID with phosphorylated NPS and active BID are essential for the multiple contributions of BRD4 to gene upregulation, particularly in cancer." (PMID 40149571, 2025). "In addition, BAZ1A complexes with SOX2 to drive the enhancer-promoter interaction and facilitate the recruitment of BRD4, thereby activating the expressions of cancer stem cells (CSCs)-related signature." (PMID 40204721, 2025). "BRD4 is an epigenetic reader protein that regulates oncogenes such as myc in cancer." (PMID 40762981, 2025). "Notably, BRD4 is highlighted due to its key role as an acetyltransferase in histone epigenetic modification, a primary focus of our group’s cancer drug development efforts." (PMID 40872497, 2025). "However, BRD4 inhibition also results in the upregulation of various genes, and the potential role of these upregulated genes in mediating cancer cell responses to BET inhibitors has been largely overlooked." (PMID 41249136, 2025). "Increased reliance on BRD4 by cancer cells to facilitate transcription at H3K27ac sites may create an increased vulnerability to BRD4 inhibitors." (PMID 41374983, 2025). "These BRD4 focal deletions appear to be the first example of a driver SV alteration that reduces toxicity in cancer, but the functional impact of these focal deletions remains unknown." (PMID 40112818, 2025). "However, we focused the remainder of our analyses on ARV-825 as both ARV-825 and ARV-771 downregulate BRD4, a key regulator in cancer cell survival and proliferation." (PMID 40649963, 2025). "BRD4, a key bromodomain-containing protein, plays a central role in mediating gene expression critical for the development and progression of various diseases, notably cancer." (PMID 39066258, 2024). "Finally, the surviving fraction of irradiated cancer cells combined with BRD4 degradation was evaluated." (PMID 38874522, 2024).
cancer (continued). "The current study demonstrates a physicochemical function of phase-separated BRD4 to limit DSBs upon either oxidative stress or irradiation; and that pharmaceutical degradation of BRD4 significantly reduced the clonogenic growth potential of irradiated cancer cells." (PMID 38874522, 2024). "BRD4 is deregulated in multiple cancers and has emerged as a promising drug target." (PMID 38191874, 2024). "Furthermore, we investigated the overlap of these significant methylation sites with transcription factor binding sites, which identified BRD4, a well-studied member of the bromodomain and extra-terminal protein family in immune diseases and cancer." (PMID 38826189, 2024). "However, inhibition of BRD4 is recognized as the most prominent effector of their action in cancer, due to the high dependency of cancer cells on the transcriptional activity of this factor." (PMID 39223828, 2024). "The therapeutic potential of BRD4 inhibitors extends beyond cancer treatment." (PMID 39066258, 2024). "For instance, H2O2-inducible PROTAC precursors release active PROTACs in cancer cells, such as A549 and H1299, leading to selective degradation of BRD4 or the estrogen receptor, inducing cytotoxicity in cancer cells while sparing H2O2-deficient normal cells, such as WI38." (PMID 39649701, 2024). "Besides, targeting epigenetic factors such as BRD4 have shown synergistic antitumor effects with PARP inhibitor in a variety of cancer treatment, such combination therapy needs further exploration in the treatment AML." (PMID 39175540, 2024). "Therefore, it has great potential to promote the ferroptosis of cancer cells and inhibit tumor development through the cooperation of BRD4 inhibitors and erastin." (PMID 38565708, 2024). "BRD4 is deregulated in multiple cancers and emerging as a promising drug target." (PMID 38191874, 2024). "Advocated by the polypharmacology concept, recentevidence discovered that a significantly synergistic effect in increasingthe death of cancer cells was observed by simultaneously perturbatingthe enzymatic activities of bromodomain-containing protein 4 (BRD4)and PARP1." (PMID 39292752, 2024). "BRD4 is highly expressed in most human cancers and can be an oncotarget." (PMID 39204415, 2024). "Consequently, BRD4 is targeted to inhibit NFκB transcriptional activity in a variety of cancer cells, and bromodomain inhibition has entered clinical trials (NCT02543879)." (PMID 39201306, 2024). "Studies in normal and cancer cells suggest a model in which p300 recruits BRD4 to hyperacetylated enhancers and super-enhancers and in turn, BRD4 augmented p300’s HAT activity, a positive feed-forward mechanism that enriches hyperacetylation of enhancers and super-enhancers." (PMID 38352301, 2024). "Our findings reveal that inhibitors of bromodomain proteins (specifically BRD4) promote OAd replication and increase virus-mediated cancer cell killing both in vitro and in vivo in preclinical models of PDAC by greatly increasing early viral gene expression, especially the essential E1A protein." (PMID 38279262, 2024). "It is well established that BRD4 regulates transcription of MYC in cancer." (PMID 38256018, 2024). "BRD4 is overexpressed in various cancer cells, such as breast, colorectal, prostate, and gastric." (PMID 38473320, 2024). "Thus, the effect of BRD4 inhibition on ferroptosis needs to be further explored in more cancer cell lines." (PMID 38565708, 2024). "Importantly, ICN1-driven T-ALL exemplifies a cancer with high BRD4 dependency wherein BRD4, cooperatively with ICN1 and MYC, drive expression of key T-ALL genes in a positive feed-forward loop to establish the leukemogenic program." (PMID 38352301, 2024).
cancer (continued). "In addition, small molecule inhibitors JQ1 and OTX015 were manufactured to induce apoptosis of BRD4-dependent cancer cells by acting on BRD4, a member of the BET protein family." (PMID 38664743, 2024). "PIN1 induces cancer metastasis and invasion by activating β-catenin, BRD4, NF-κB, and p53M." (PMID 39202474, 2024). "DUB3 stabilizes BRD4 through deubiquitination and promotes cancer progression." (PMID 38893083, 2024). "Bromodomain-containing 4 (BRD4), a transcriptional and epigenetic regulator, is over-expressed in IBD, and studies in cancer cells suggest that BRD4 might positively control IL-34 expression." (PMID 39451216, 2024). "The Ino80 complex is a highly conserved ATP-dependent chromatin remodeling complex, involved in transcription, replication, and DNA repair while Ino80 contributes to activation of super-enhancers in the context of cancer, a feature shared with Brd4 in the context of senescence." (PMID 38534794, 2024). "In the present study, we chose BRD4 as the starting point to construct the AL139294.1–miR-204-5p–BRD4 interaction axis, because BRD4 is a well-known tumour-associated gene, and its upregulation is closely related to the development of various cancers." (PMID 38229152, 2024). "This broad tissue distribution is a unique property of NC compared with many other fusion gene-driven cancers and indicates that the BRD4::NUTM1 fusion gene may transform a broad range of cell types covering all three germ layers." (PMID 38724194, 2024). "Importantly, more than a dozen BRD4 inhibitors have entered clinical trials in patients with cancer of various organ origins." (PMID 38135679, 2023). "Inhibition of BRD4 blunts the YAP1/TAZ-mediated aggressive behavior of TNBC cancer cells." (PMID 37770435, 2023). "Therefore, BRD4 is able to support the proliferation and survival of cancer cells, and targeting BRD4 has shown to be effective in the eradication of tumor cells in preclinical studies." (PMID 37685868, 2023). "BRD4 has been proposed as a druggable promising target in human cancer." (PMID 37737256, 2023). "BRD4 (bromodomain-containing protein 4) is an epigenetic reader that realizes histone proteins and promotes the transcription of genes linked to cancer progression and non-cancer diseases such as acute heart failure and severe inflammation." (PMID 37570684, 2023). "In addition to its direct effects on cancer cells, recent evidence suggests that inhibition of BRD4 polarizes TAMs into the M1-like phenotype by inhibiting transcription factors that modulate the phenotype of M2 macrophages including MAF, IRF4, and AKT." (PMID 37685868, 2023). "BRD4 inhibitors have demonstrated promising potential in cancer therapy." (PMID 38099141, 2023). "Dual Brd4-kinase inhibitors may be particularly useful for treating cancers with acquired resistance to single-activity tyrosine kinase or BET inhibitors." (PMID 37049806, 2023). "In addition to its regulation of gene expression, recent research has proved that BRD4 is also involved in other cellular functions that play a role in cancer progression." (PMID 37765111, 2023). "Furthermore, in esophageal adenocarcinoma, BRD4 activates the Hippo/YAP1 signaling pathway—one of the primary regulators of cancer aggressiveness and stemness." (PMID 36674511, 2023). "The cancer results from a fusion of BRD4 or BRD3 on chromosome 15q14." (PMID 37834411, 2023). "In preclinical studies, MYC is a well-known Brd4 target gene in multiple cancer types." (PMID 37049806, 2023). "Interestingly, BRD4 has been reported to enhance the transcription of PD-L1 in different types of cancers." (PMID 37603071, 2023). "JQ1, a BET inhibitor targeting BRD4, suppresses angiogenesis in various cancer types." (PMID 37509231, 2023).
cancer (continued). "In cancer cells, the BRD4 inhibitor JQ1 induces ferroptosis by enhancing the expression of an HDAC named SIRT1, which decreases the H3K27ac level at upstream of BRD4, ultimately affecting the recognition of acetylation sites on the histones at GPX4 and SLC7A11 genes." (PMID 37229485, 2023). "Many studies have shown that bromodomain and extracellular domain inhibitors (BETi) treatments involve reversible binding and incomplete inhibition of BRD4, which may impair BETi activity in cancer cells." (PMID 36770884, 2023). "As a result, the identification of potential novel BRD4 dual-target inhibitors could be a fruitful approach to treating cancer." (PMID 37765111, 2023). "MANCR may also serve as a pivotal target for the bromodomain and extra-terminal (BET) protein BRD4, exerting a crucial influence on cellular migration and the invasive properties of cancer." (PMID 38203269, 2023). "Interestingly, we did not observed difference between the HA-EV and HA-NPM1 groups when treated with JQ1, which is consistent with the previous result that NPM1 regulated cancer cell growth through BRD4." (PMID 37875480, 2023). "The BRD4 breakpoints in each cancer provide evidence of a fusion oncogene mechanism involving BDR4." (PMID 37834411, 2023). "The inhibition of BRD2, BRD3, and BRD4 shortens signaling between super-enhancer regions and oncogene target promoters, resulting in cell-specific inhibition of oncogene expression and ultimately cancer cell death." (PMID 36793283, 2023). "In addition, BRD4 forms SEs at cancer stemness genes by carefully colocalizing with MED1 and p65 in SCC cells." (PMID 37501079, 2023). "Next, we analyzed a broader cancer cell panel to determine whether there was a consistent inverse correlation between BRD4 and LOXL2 expression." (PMID 37937685, 2023). "The BRD4 inhibitors show anticancer effects in clinical trials as monotherapy, but it is now clear that BRD4 inhibitors need to be combined with other anticancer agents to effectively treat cancer patients." (PMID 38135679, 2023). "However, the importance of BRD4 in cancer goes beyond regulating transcription as this protein is a custodian of genomic integrity." (PMID 37501079, 2023). "This could explain why NUT::NSD3 fusion positive carcinomas outside the thorax appear to have a significantly better prognosis than their NUT::BRD4 positive counterparts." (PMID 37118352, 2023). "It has been reported that the occurrence and development of cancer depends in part on the mechanism by which BRD4 can specifically recognize and anchor the side chain acetylated lysine on superenhancer open chromatin to promote the transcription of the MYCN gene." (PMID 36438198, 2022). "The treatment of HPV+ head and neck cell lines with JQ1, the inhibitor of the BRD4 (Bromodomain Containing 4) protein that recognizes the H3K27ac histone mark, is able to downregulate cancer-specific AS isoforms and eventually inhibits tumor cell proliferation." (PMID 35955433, 2022). "Thus, the role of BRD4 in cancers is recognized to involve the regulation of SE organization and oncogene expression." (PMID 35159127, 2022). "BRD4 inhibition is thereby more effective in cancer cells with high AR activity and dependency." (PMID 36139513, 2022). "In line with our speculation, cRGD-P/DOX-induced BRD4 expression is responsible for DOX resistance, and the BRD4 degrader ARV-825 could relieve drug resistance to improve the cytotoxic effect of DOX in the treatment of cancer." (PMID 36157053, 2022). "BRD4, the most studied protein is dysregulated in numerous diseases, and the major one is cancer." (PMID 35401196, 2022). "Notably, ACP-1n showed the ability to suppress BRD4 assembly, resulting in the prevention of cancer cell growth with simultaneous reduction in nucleus size." (PMID 35159127, 2022).